NLRP3 (NLR family pyrin domain containing 3)
Diseases named in the same sentence as NLRP3 in open-access papers (continued):
Sharing a sentence is not in itself a finding about the gene and the disease.
ischemia (122 papers, 2012 to 2025). A hypoperfusion of the BLOOD through an organ or tissue caused by a PATHOLOGIC CONSTRICTION or obstruction of its BLOOD VESSELS, or an absence of BLOOD CIRCULATION. "Earlier studies have shown that MINO can effectively prevent brain damage caused by cerebral hemorrhage or ischemia by inhibiting the activation of the NLRP3 inflammasome." (PMID 38329438, 2024). "Existing research has shown that reoxygenation following ischemia causes tissue oxidative stress and that the ROS-induced NLRP3 inflammasome can aggravate myocardial I/R injury by initiating pyroptosis and sterile inflammatory responses." (PMID 35422485, 2022). "In the presence of ischemia associated with a myocardial injury, cell death and cell debris act as damage associated molecular patterns (DAMPs) that are sensed by NLRP3 and induce its activation." (PMID 34207886, 2021). "So far, the mechanism that activates NLRP3 inflammasome in ischemia injury generalizations in two main models, lysosomal damage or ROS release, is mutually connected and associated with NLRP3 in ischemia injury." (PMID 30140326, 2018). "Mechanistically, the protective effect of HSYA in alleviating myocardial injury after ischemia may be associated with NLRP3 inflammasome, Bcl-2, Bax, caspase-3, eNOS proteins, and TLR/NF-κB, Nrf2/HO-1, JAK/STAT, PI3K/Akt, AMPK/mTOR, VEGFA pathways." (PMID 40271057, 2025). "Beta-asarone reduces cardiac inflammation and diminishes the size of MI by inhibiting the NLRP3 inflammasome, thus enhancing cardiac recovery after ischemia reperfusion." (PMID 39925805, 2025). "Previous studies have demonstrated that hepatic ischemia–reperfusion injury can induce damage to distant organs, including the hippocampus and cortex, through activation of NLRP3 inflammatory vesicles and neuronal focal death." (PMID 40778222, 2025). "Colchicine mitigates inflammation triggered by ischemia by indirectly inhibiting NLRP3 oligomerization, which reduces the production of IL-1β and IL-18." (PMID 40149903, 2025). "In ischemia-reperfused myocardial tissues, there was a reduction in microRNA-495 expression, which facilitates the activation of the NLRP3 inflammasome, worsening inflammatory damage and apoptosis in CMECs." (PMID 39925805, 2025). "The control hearts and hearts previously exposed to ticagrelor were perfused with buffer containing the NLRP3 inhibitor INF for twenty minutes before thirty minutes of global ischemia and sixty minutes of reperfusion." (PMID 38791515, 2024). "In a mouse ischemia/reperfusion model, hypoxic preconditioning decreased pyroptosis to prevent inflammatory injury by inhibiting the expression of the NLRP3 inflammasome and the related proteins Caspase-1 and Gasdermin D." (PMID 38317957, 2024). "(2023) discerned through transcriptomic analysis of mouse retina that IncRNA (181-Rik) mitigates ischemia-reperfusion injury (IR) by quelling NLRP3 inflammatory pathway activation." (PMID 39220368, 2024). "Specifically, the NLRP3 inflammasome has been shown to be activated in the context of ischemia and related LV dysfunction." (PMID 38306359, 2024). "One likely mechanistic explanation is that NLRP3 positive neutrophils are able to produce NETs which occlude the penumbra cardiac microvasculature, thus increasing the region of ischemia." (PMID 38914598, 2024). "Six-week treadmill running significantly decreased the NLRP3 levels in the ischemia–hypoxia + exercise as compared with the ischemia–hypoxia group (P<0.05)." (PMID 36742136, 2023). "Here, consistent with previous studies, our results showed that NLRP3 inflammasome expression and activity were elevated in ischemia-reperfused kidneys, which exhibited increased clustering of NLRP3 inflammasomes on the mitochondria and the MAMs." (PMID 36801911, 2023).
ischemia (continued). "These extensive publications indicate that NLRP3 regulates microglia/macrophage polarization through the nf–κb pathway, specifically by promoting M1 macrophage polarization to exacerbate ischemia–reperfusion injury." (PMID 37088947, 2023). "Consistently, some studies showed that inhibition of NLRP-3 inflammasome has reduced the ischemia/recanalization (I/R) injury and protected the BBB in both in vivo and in vitro ischemic conditions." (PMID 37822799, 2023). "NaHS use reduced the pyroptosis of retinal cells and brain neurons through inhibition of the NLRP3/caspase-1/GSDMD signaling pathway in an ischemia/reperfusion injury model." (PMID 37445920, 2023). "In particular, nucleotide-binding oligomerization domain (NOD)-like receptor (NLR) pyrin domain-containing 1 (NLRP1) and 3 (NLRP3) inflammasomes, are overexpressed in the brain following ischemia." (PMID 37822799, 2023). "It is reported that H2S can reduce neuronal inflammation by inhibiting the NLRP3/caspase-1/GSDMD signaling pathway in ischemia/reperfusion brain injury." (PMID 37445920, 2023). "Pharmacological inhibition of the NLRP3 inflammasome via an NLRP3 inflammasome inhibitor (16673-34-0), an intermediate in the synthesis of glyburide, limits cell death and left ventricle systolic dysfunction after ischemia in mice." (PMID 35273164, 2022). "Some scholars believe that TXNIP/NLRP3 axis is involved in renal ischemia-reperfusion injury and T2DM cardiomyopathy in diabetic rats." (PMID 35845136, 2022). "So, we used immunohistochemistry to detect NLRP3, Caspase-1 and IL-1β levels in the right striatum of ischemia region." (PMID 33461169, 2021). "NLRP3 KO attenuated rat myocardial I/R injury through reducing the infarct size induced by ischemia." (PMID 34445481, 2021). "The mechanism research showed that the levels of NLRP3, caspase-1, IL-1β and IL-18 were all increased in rat brain with I/R injury, which was ischemia for 1 h and then reperfusion for 24 h." (PMID 34445481, 2021). "An understanding of how stress alters NLRP3 activation and autophagy, thus priming the microglial inflammatory response to ischemia, is needed." (PMID 32466385, 2020). "At day 7, global ischemia-induced NLRP3 inflammasome activation, as evidenced by an increase in the expression of NLRP3, and IL-1β in the hippocampus compared to Sham controls." (PMID 32466385, 2020). "Not only that a growing number of studies have shown that the NLRP3 suppression serves as neuroprotective role in ischemia stroke through alleviating infarction volumes and neurovascular damages to improve ischemia outcomes." (PMID 32908485, 2020). "NOD-like receptors (NLR) are intracellular sensors of the innate immune system, with the NLRP3 being a pro-inflammatory member that modulates cardiac ischemia-reperfusion injury (IRI) and metabolism." (PMID 33362773, 2020). "It plays a protective role in ischemia-induced myocardial injury by inhibiting the NLRP3 inflammasome through suppressing ROS and TXNIP." (PMID 32650482, 2020). "Activation of the nucleotide-binding oligomerization domain-like receptor (NLR) family pyrin domain containing 3 (NLRP3) inflammasome cascade has a role in the pathogenesis of ischemia/reperfusion (IR) injury." (PMID 31319469, 2019). "Together, these data show a marked inflammatory response in the brain after ischemia and significant upregulation of the NLRP3 system." (PMID 31009361, 2019). "We found that MCC950 was able to reduce neutrophils and monocytes that expressed NLRP3 in the brain and spleen after ischemia." (PMID 31787973, 2019).
ischemia (continued). "Recently, baicalin was found to effectively downregulate the expression of NOD2 receptor and TNF-α in neurons suffered ischemia-reperfusion injury and inhibit activation of NLRP3 inflammasome in macrophages." (PMID 30647760, 2018). "NLRP3 expression and activation also increase in the brain after direct trauma or following ischemia in rodent models, and NLRP3 knockdown leads to a reduction of brain damage and inflammatory mediators in animal models." (PMID 30166988, 2018). "In the present study, we used the neonatal cardiomyocytes models of ischemia-like conditions to evaluate the mitochondrial fission and the activation of the NLRP3 inflammasome." (PMID 27973457, 2016). "In addition, a recent study points to a crucial role of the NOD‐like receptor family pyrin domain‐containing 3 (NLRP3) inflammasome in the inflammatory damage following ischemia." (PMID 40804606, 2025). "Moreover, the NLRP3 inflammasome plays a critical role in the ischemia-induced breakdown of the blood-brain barrier." (PMID 40606597, 2025). "Moreover, activation of inflammasome-mediated IL-1β secretion aggravates intestinal ischemia-reperfusion injury by inhibiting autophagy in mice, whereas knockdown of NLRP3 reverses these effects." (PMID 40362581, 2025). "Western blot results showed that not only the expression of pyroptosis-related proteins such as NLRP3 and cleaved caspase-1 was increased in the retinal neurons with ischemia/reperfusion injury in vivo and in vitro, but also the expression of NLRP3 and cleaved caspase-1 was increased." (PMID 40236697, 2025). "Additionally, studies have elucidated that PAD4, P38 and ERK can activate various inflammatory pathways, including microglia, TLR4, NF‐κB and NLRP3 pathways, culminating in an inflammatory cytokine storm that exacerbates ischemia‐induced cerebral injury." (PMID 39099086, 2024). "Targeting neutrophil NLRP3 and the pathways that help its assembly may be a new therapeutic strategy to reduce ischemia-related cardiac damage." (PMID 38914598, 2024). "It is postulated that this phenomenon may be attributed to the specific effects of NLRP3 in diverse tissues, degrees of ischemia, and cell types." (PMID 39139639, 2024). "Moreover, genetic deletion or pharmacological inhibition of S100A8/A9 can inhibit the TLR4/NLRP3/IL-1β pathway, suppressing ischemia-induced granulopoiesis and improving cardiac dysfunction." (PMID 36768433, 2023). "Recent studies have also supported the activation of the NLRP3 inflammasome and NLRP3 inflammasome-mediated pyroptosis following ischemia, which modulate the polarity and distribution of aquaporin-4 in the infarct area, leading to an increased BBB permeability." (PMID 36676165, 2023). "It has been reported that in a mouse ischemia reperfusion injury model, NLRP3 inflammasome formation could be detected 24 h after reperfusion." (PMID 37108494, 2023). "RSV via targeting NLRP3 inflammasome activation could inhibit ischemia-induced myocardial senescence signals." (PMID 36238294, 2022). "Upregulated HSPA2 exerted a neuroprotective effect through its regulation of endocytosis in a rat middle cerebral artery occlusion model, and inhibition of HSPA8 would protect against spinal ischemia–reperfusion injury via astrocyte NF-κB/NLRP3 inflammasome pathway." (PMID 36120453, 2022). "However, we recently showed that NLRP3 plays a dual time-dependent role in brain injury, using an experimental ischemia model." (PMID 35893807, 2022). "Moreover, idebenone attenuates NLRP3 inflammasome activation induced by ischemia in an ischemia/reperfusion rat model." (PMID 35222363, 2022). "Recent studies indicated NLRP3 inflammasome could also polarize microglia and exacerbate ischemia/hemorrhage-induced brain injury." (PMID 35620574, 2022). "Inhibition of NLRP3-inflammasome is reported to alleviated the brain injury in ischemia." (PMID 34852714, 2021).
ischemia (continued). "Therefore, NLRP3 inflammasome appears to be a unique, promising therapeutic target for CA/CPR, which causes whole-body ischemia/reperfusion and affects all organs." (PMID 32867797, 2020). "In our study, NLRP3 inflammasome activation peaked at 14 days post-ischemia." (PMID 32466385, 2020). "In contrast, no protective effects nor NLRP3/RISK modulation were recorded when Ticagrelor was administered before ischemia in isolated heart, indicating that Ticagrelor direct target is not in the myocardium." (PMID 32832010, 2020). "MSCs have been noted for ischemia reperfusion injury, and good results have been obtained, which could decrease NLRP3 activation via clearing excessive ROS as reported." (PMID 32849879, 2020). "Furthermore, the neurologic score was consistent with the mRNA transcription levels of NLRP3, IL-1β, and caspase-1 in the ischemia core." (PMID 29853850, 2018). "In fact, when comparing the 20 min reperfusion and the 60 min reperfusion models we observed a progressive expression and activity of NLRP3 inflammasome complex, thus confirming previous findings on the timing of NLRP3 inflammasome formation in the heart during ischemia reperfusion." (PMID 28053692, 2016). "Moreover, pretreatment with oridonin suppressed the overactivation of OS and NLRP3 inflammasome, consequently mitigating cardiac pathological alterations induced by ischemia reperfusion, including the alleviation of myocardial inflammatory damage and reduction of infarct size." (PMID 39925805, 2025). "Therefore, the objective of this study was to confirm whether HS plays an anti-inflammatory role by inhibiting ROS, thereby restraining the NLRP3 inflammasome, and whether it can protect the brain from ischemia injury in mice." (PMID 37371417, 2023). "Therefore, Nrf2 could function as a protective mediator of NLRP3 inflammasome activation, which may represent an innovative therapeutic insight for ischemia treatment." (PMID 36160384, 2022). "However, injecting MCC950, an inhibitor of NLRP3, could resist hepatic ischemia–reperfusion or IRI-Exo injury." (PMID 36292924, 2022). "Various studies using different approaches such as gene deletion, fasting or antibody application against NLRP3 highlighted a marked improvement of the post-ischemic inflammatory status and motor functions, which significantly reduced the infarct sizes in rodent ischemia models." (PMID 32645874, 2020). "Therefore, we investigated how miR-223 and NLRP3 might function in kidneys exposed to conditions of ischemia and subsequent reperfusion." (PMID 28619106, 2017). "Our results suggest that STS inhibits the activity of NLRP3 inflammasome through the suppression of TXNIP expression, which is similar to the conclusion that STS protects against ischemia/reperfusion myocardial injury by inhibiting the TXNIP over-expression." (PMID 37697234, 2023). "NLRP3 was positive in cells expressing 12/15-LOX both in the acute and subacute phases of ischemia-recanalization." (PMID 37822799, 2023). "This led to a greater increase in TLR4, P2X7, IκBα activation, NLRP3, ASC, cleaved caspase-1, and pro-inflammatory cytokine IL-1β levels in the Stress+ISCH group compared to the ischemia-alone group." (PMID 32466385, 2020). "Astragaloside IV has been reported to attenuate NLRP3 and caspase-1 activation and decrease IL-1β and TNF-α release in a mouse model of ischemia and reperfusion." (PMID 32650482, 2020). "The present study was designed to investigate the role of TXNIP during ischemia AKI in diabetic models and examine a key role of TXNIP in bridging redox signals with activation of NLRP3 inflammasome in AKI injury." (PMID 27867451, 2016).
ischemia (continued). "We also examined the effect of TXNIP on NLRP3 activation; after ischemia AKI injury, kidney NLRP3 inflammasome expression was dramatically increased in both DI/R rats and NI/R rats as compared to rats of each sham group." (PMID 27867451, 2016). "Inhibition of HMGB1 significantly suppressed the expression of NLRP3, ASC, and the maturation of caspase-1 in ischemia retinal tissue." (PMID 26224068, 2015). "A number of distinct inflammasome types have been identified, although only NLRP1 and NLRP3 have been indicated to be upregulated during cardiac ischaemia and reperfusion, acting as key contributors to myocardial IRI, with NLRP3 being the most extensively studied and recognised." (PMID 39273196, 2024). "Overexpression of Homer1 could inhibit ER stress-related TXNIP/NLRP3-mediated pyroptosis by regulating the AMPK signaling pathway, which in turn improved the visual function of the retina after ischemia." (PMID 38069134, 2023). "Notably, MET has been indicated in previous studies to reduce cell pyroptosis via NLRP3-GSDMD axis, thus protecting against intestinal ischemia-reperfusion injury." (PMID 36815949, 2023). "Genetic deletion of NLRP3 failed to reduce infarct size in a closed-chest in situ mouse heart model (30 min ischemia/3 h reperfusion), which was attributed to its low expression in heart tissue." (PMID 36835212, 2023). "NLRP3 activation appears to be important for inducing a proper inflammatory response, as NLRP3 KO animal mortality increases after CNS injury, but the selective inhibition of NLRP3 activation using MCC950 1 h after the ischemia is protective." (PMID 35893807, 2022). "Moreover, functional inhibition of NLRP3 is compensated by an upregulation of NLRC4 and AIM2 after ischemia." (PMID 34628598, 2022). "Besides NLRP3, AIM2 and NLRC4 seem to play a crucial role after ischemia and are regulated by E2 and P." (PMID 32645874, 2020). "Recently, it has been reported that Nlrp3 regulates chemokine-mediated functions and recruitment of neutrophils contributing to hepatic ischemia-perfusion injury independent of inflammasome." (PMID 27926940, 2016). "As triggers for the innate immune NLRP3 inflammasome protein complex appear to overlap with those for cardiac ischemia-reperfusion (I/R) and ischemic preconditioning (IPC), we explored the possibility that the NLRP3 inflammasome is involved in IPC and acute I/R injury of the heart." (PMID 22848390, 2012). "CD8+ T‐cell functions as an important mediator of ischemia‐induced angiogenesis via the modulation of inflammation, oxidative stress, proteolysis, and endothelial proliferation that might be mediated by the IFN‐γ/NLRp3‐caspase‐1 and VEGF/Erk1/2 axes." (PMID 41243839, 2025). "We found that, at the early stage of ischemia, OPN expression was enhanced, especially in microglia, and colocalized with LAMP1 and GAL-3, which was accompanied by lysosomal damage, CTSB release, NLRP3 inflammasome activation, and autophagosomes accumulation after HI insult." (PMID 36980197, 2023). "Taken together, most studies supported that NLRP3 inflammasome can mediate and amplify the inflammatory response and cell pyroptosis, thus aggravating myocardium damage and promoting ventricular remodeling after ischemia with or without reperfused myocardium." (PMID 35464402, 2022). "Nevertheless, our findings overlap but are distinct from a previous study, which demonstrated that RLX could attenuate caspase-1 activity in an in vivo model of ischemia/reperfusion injury via an eNOS-dependent mechanism, in which the direct involvement of the NLRP3 inflammasome was not provided." (PMID 32848798, 2020). "To determine whether stress-induced HMGB1 release primes, the NLRP3 inflammasome in rats subjected to global ischemia, and whether PROG treatment modulates stress priming, we investigated the NLRP3 inflammasome signaling pathway in the hippocampus on days 7 and 14 after global ischemia." (PMID 32466385, 2020).
ischemia (continued). "However, the role of NLRP3 in AMI is also time-dependent, and Nlrp3 deficiency did not play a protective role during the first few hours of AMI due to low cardiac expression at the onset of ischemia, which was consistent with the 2-step process required for activation." (PMID 35464402, 2022).